ETS1 (ETS proto-oncogene 1, transcription factor)
Diseases named in the same sentence as ETS1 in open-access papers (continued):
Sharing a sentence is not in itself a finding about the gene and the disease.
tumor (continued). "WTAP can cause posttranscriptional repression of ETS proto-oncogene 1 (ETS1) through m6A modification and promote the proliferative capacity and tumor growth of HCC cells through the WTAP/ETS1-p21/p27 axis." (PMID 39229278, 2024). "HIF-1α/HIF-2α correlated to a far greater extent with the two VEGF receptors and ETS-1 in the tumor tissue compared to the peritumor tissue, their level of association with VEGF-A was identical in both sample groups." (PMID 38607072, 2024). "It has been affirmed that abnormal expression of ETS1 participated in tumor proliferation, metastasis, and EMT in several types of cancer, including PDAC." (PMID 38057853, 2023). "To validate these results, we transferred OT-I cells transduced with sgNTC, sgEts1, sgBatf or sgEts1 with sgBatf OT-I cells into B16-OVA tumour-bearing mice and found that targeting both Ets1 and Batf reversed the increased accumulation of total and Tex cells." (PMID 37968405, 2023). "In colon cancer tissues, tumor‐associated fibroblasts generate chemokine ligand 2, which acts on its receptor on the tumor surface to enhance the transcription of FGFR4 in an Ets‐1‐dependent manner, thereby activating the β‐catenin pathway to lead to EMT." (PMID 37750089, 2023). "The combinatorial treatment of OT-I cells deficient for Ets1 with anti-PD-L1 enhanced antitumour effects compared with control groups in B16-OVA and E.G7-OVA tumours, which suggested that targeting Ets1 in CD8+ T cells enhances the ICB response." (PMID 37968405, 2023). "It is worth mentioning that MTBP can up-regulate the expression levels of ETS-1 downstream genes in HCC tumor tissue." (PMID 36106099, 2022). "The methyl transferase METTL3 is up-regulated in brain tumors leading to the methylation of CPEB2 mRNA, which in turn stabilizes the splicing factor SRSF5 mRNA, leading to the incorporation of exon 7 in ETS-1 in models of the Blood–Tumor Barrier." (PMID 36064747, 2022). "ETS1 is highly expressed in a variety of tumor tissues, and inhibiting ETS1 can block tumor proliferation, migration, and invasion in vivo." (PMID 36064747, 2022). "Tet2 reshapes the chromatin accessibility of several key TFs at genomic binding regions, including BATF and ETS1 in CD8+tumor-infiltrating lymphocytes, thereby enhancing its anti-tumor immune function and suppressing melanoma growth in vivo." (PMID 36203205, 2022). "As a result, our findings shed insight on ETS1's latent involvement in tumor immunology and its potential application as a cancer biomarker." (PMID 35463077, 2022). "Next, the effect of MTBP on the in vivo proliferation of Huh-7 cells or the ETS-1 pathway in tumor tissues was examined by using the subcutaneous tumor models." (PMID 36106099, 2022). "Targeting Ets1 in cancer treatment has been proposed, and the myriad ways by which downregulation of Ets1 protein inhibits tumor progression." (PMID 36305724, 2022). "The ETS-1 gene is involved in cell growth and extracellular matrix invasion, which can promote tumor invasion and metastasis." (PMID 36211008, 2022). "Many strategies which target the reduction of Ets1 protein level as a tumor treatment option have been studied." (PMID 36305724, 2022). "MiR-9 suppresses the expression of cyclin D1 and Ets1 by binding to their 3′-UTRs; it has been seen that it leads to the inhibition of proliferation, invasion, and metastasis processes in tumor cells." (PMID 36551878, 2022). "Recently, increasing attention has been paid to the regulatory role of ETS1 in the energy metabolism of tumor cells." (PMID 35212617, 2022). "Although Ets-1 is mostly known as a prooncogenic TF, several studies have reported a paradoxical tumor-suppressive role of Ets-1 as well." (PMID 35789155, 2022). "Genes significantly associated with the outcomes were enriched for early estrogen response pathway, DNA repair pathways as well as targets of transcription factors such as E2F4, MYC, and ETS1 that have recognized roles in tumor characteristics and survival." (PMID 36584096, 2022).
tumor (continued). "We will look into the genetic abnormalities, expression patterns, and survival assessments of ETS1 expression in pancancer patients, as well as the relationship between ETS1 expression and tumor immune infiltration." (PMID 35463077, 2022). "Our findings also provide insight into ETS1's important involvement in carcinogenesis and metastasis and a proposed mechanism through which ETS1 expression modulates tumor immunology and metabolic activity." (PMID 35463077, 2022). "Subsequently, a series of bioinformatic technologies and molecular experiments indicated that miR-155-5p as the target gene of AFAP-AS1 influenced tumor progress by regulating the classic tumor- related transcription factor ETS1." (PMID 33999777, 2021). "ETS1 contributes to tumor angiogenesis and invasion and migration of cancer cells, and promotes epithelial-mesenchymal transition (EMT) and the development of drug resistance." (PMID 34659572, 2021). "In accordance with upregulation of ETS1 in tumor ECs, ETS1 expression was higher in microvascular proliferation region where tumor ECs were enriched due to active angiogenesis." (PMID 34867089, 2021). "It has been shown that expression of ETS1 in tumor cells promotes vascular mimicry by induction of receptor for vascular endothelial growth factor." (PMID 34867089, 2021). "Previous researches showed that as a transcription factor, the downstream of ETS1 were several classic tumor-related genes, such as RAS, MET, ERK and etc." (PMID 33999777, 2021). "ETS1, a transcription factor with transcriptional activation, is involved in many biological functions, such as tumor cell proliferation, apoptosis, invasion, metastasis, and angiogenesis." (PMID 34659572, 2021). "Three of them, ETS1, MYCN and TFAP2A, have been previously associated with the cancer progression and all of them show tumour promoting effects." (PMID 34198662, 2021). "Previous studies have shown that the transcription factor ETS1 is involved in tumor progression and metastasis through the transcriptional regulation of EMT-related genes in several cancers, including PCa." (PMID 34696782, 2021). "Upregulation of ETS1 in tumor vasculature was further confirmed in protein level by immunohistochemical staining of our in-house samples including 18 GBM tumors and paired control brain tissue." (PMID 34867089, 2021). "In accordance with in vitro findings, galunisertib treatment decreased Ets1 level in tumor vessels in vivo." (PMID 34867089, 2021). "Suppressive action has also been demonstrated in ESCC through the action on c-Myc, and in gastric cancer where miR-145 suppression increases Ets1 expression, facilitating in this way tumor metastasis and angiogenesis." (PMID 34199293, 2021). "Hypoxia in the tumor microenvironment leads to miR-4521 downregulation via inducing ETS1 and this miRNA can reduce hypoxic response of tumor cells." (PMID 33407516, 2021). "When ETS1 was silenced, metastatic nodule formation in the peritoneal cavity was reduced, as evidenced by the diminished luminescence signal and reduced tumor number and size relative to control group." (PMID 33407516, 2021). "Targeting REST and ETS1 for the therapeutic modulation of tumor angiogenesis is a topic for future studies." (PMID 33469989, 2021). "We found that conditioned medium from GBM tumor cells was sufficient to upregulate Ets1 expression in bEND.3 cells, suggesting a direct effect of tumor cell on Ets1 expression in ECs." (PMID 34867089, 2021). "Previous studies have shown that the transcription factor ETS1 is involved in tumor progression and metastasis through EMT induction in various cancers, including hepatocellular carcinoma and colon cancer." (PMID 34696782, 2021). "Hypoxia in the tumor microenvironment contributed to miR-4521 downregulation in an ETS1-dependent manner and miR-4521 mitigated hypoxia-mediated metastasis." (PMID 33407516, 2021).
tumor (continued). "This study fully confirmed the effectiveness of Ets-1 as a broad-spectrum tumor recognition signal and provided a new anti-cancer tool based on the CRISPR system." (PMID 34124154, 2021). "The differences in the regulation of ETS1 in different cell lines of the same cancer phenotype shows the broader aspect of tumor heterogeneity, which occurs in tumors of different origin and mutation." (PMID 34136678, 2021). "Agminated transcription factor ETS1 would induce angiogenesis and neoplastic cell migration to contribute to tumor progression through upregulating KIF14 expression." (PMID 34712225, 2021). "As one of the most widely studied transcription factors in the Ets family, Ets-1 is involved in cell proliferation and apoptosis, angiogenesis, and tumor progression." (PMID 34820381, 2021). "Our data revealed that SLC26A4‐AS1 overexpression reduced tumour volume and weight while its combination with ETS1 knockdown abrogated the reduction." (PMID 34378314, 2021). "Taken together, our data elucidated that SLC26A4‐AS1 promoted autophagy and suppressed PTC tumour growth through ETS1‐mediated ITPR1 regulation." (PMID 34378314, 2021). "Intriguingly, we found that tumor specimens showed significantly higher methylation levels in two CpG island regions, located around the promoter of ETS1 (locus #1 and locus #2), compared to normal specimens." (PMID 32477936, 2020). "MiRNA-143 targets a number of tumorigenic genes including c-Myc, ERG and Ets-1 and is classed as a tumor suppressor." (PMID 31979312, 2020). "ETS1, an essential member of the ETS transcription factors, participated in a variety of crucial biological processes underlying tumor progression, such as cell invasion, epithelial–mesenchymal transition, angiogenesis, and drug resistance." (PMID 31894857, 2020). "ETS1 is known to enhance the expression of numerous tumorigenic genes involved in tumor angiogenesis, cancer cell invasion, and energy metabolism." (PMID 32477936, 2020). "Our findings, therefore, raise the possibility that ETS1 amplifies the tumor-promoting effects of these mutants by increasing their expression and, indeed, ETS1 gains are common in the ABC-DLBCL cluster 5 characterized by MYD88 and CD79A/B." (PMID 32679859, 2020). "In this study, we defined ETS1 as the tumor suppressor in BRCA together with detailed molecular action mechanisms." (PMID 32477936, 2020). "To take a step forward from this analysis, we have identified a unique feature of ETS1 to inhibit tumorigenesis of BRCA cells by directly trans-activating core regulators of tumorigenesis as tumor suppressor genes in BRCA cells." (PMID 32477936, 2020). "The tumor-enriched expression of ETS1 was most strikingly discernible in the RNA-Seq data from the Cancer Genome Atlas (TCGA), where ETS1 levels were higher in ~80% of the patient tumor samples compared to matched normal tissue." (PMID 31306413, 2019). "Knock-down experiments and ChIP corroborated the notion of a functional role for ETS1 and, accordingly, all double-mutant tumor cells were highly sensitive towards the ETS-factor inhibitor YK-4-279." (PMID 31391125, 2019). "Elevated levels of expression are observed in tumor progression, resulting in Ets-1 being named an oncoprotein." (PMID 30857266, 2019). "Expression of ETS1 in tumor tissues was identified to be lower compared with paratumor tissues in HCC." (PMID 31438961, 2019). "It has been reported that ETS-1 plays an important role in promoting tumor invasion in both laryngeal and oral squamous cell carcinomas." (PMID 31118072, 2019). "We further found that a higher ETS1 RNA level was observed in LUAD tissues than in non-tumor tissues." (PMID 31889958, 2019).
tumor (continued). "The expression of the transcriptional regulator, E26 transformation-specific 1 (ETS1), is elevated in many epithelial cancers and portends aggressive tumor behavior and poor survival." (PMID 31306413, 2019). "High expression of ETS1 was found to correlate to poor clinical outcomes, such as increased distant metastasis and higher tumor grading in lung cancer." (PMID 31889958, 2019). "Epcam+ cells were enriched for tumor-related motifs Klf14, Mitf, Ets1, Nrf2, and Nrf1 binding motifs." (PMID 31594952, 2019). "We identified a core-regulatory element (CRE) on the Ets1 promoter and elucidated its functional importance in tumor invasiveness." (PMID 30467308, 2018). "Deletion of the CRE region by CRISPR/Cas9 system resulted in significant reduction in Ets1 expression, which led to alterations of Ets1-mediated transcription programs including tumor invasiveness-related genes." (PMID 30467308, 2018). "Multivariate analysis confirmed that a higher ETS1 expression level (HR = 1.51; 95% CI = 1.05–2.20; p = 0.028) and a larger tumour size (HR = 1.53; 95% CI = 1.34–1.97; p = 0.036) were substantially correlated with overall survival." (PMID 30082686, 2018). "As expected, either Ets-1 or Usp9x overexpression in SK-Mel29 cells increased 3D tumour growth, while Ets-1 KD blocked both control and Usp9x-enhanced 3D growth and colony formation." (PMID 28198367, 2017). "One common target, Ets-1, was pursued based on its biologic role in tumour expansion and involvement in the RAS/MEK/ERK pathway." (PMID 28198367, 2017). "ETS1, a member of the ETS transcription factor family, has been implicated in tumor angiogenesis and vascularization as a positive response to the hypoxic microenvironment caused by inflammation in tumor tissues." (PMID 29340052, 2017). "Usp9x inhibition is expected to add to the treatment options for patients with Ets-1-overexpressing tumours, particularly when used in rational, biologically based combinations." (PMID 28198367, 2017). "Another pathway HGF/c-MET/ETS-1 also plays a central role in tumor proliferation, invasion and metastasis." (PMID 27824903, 2016). "When GATA4 and ETS1 were depleted, the tumor propagation and formation were significantly inhibited." (PMID 26625313, 2016). "Nevertheless, the expression profile of MLL mutated tumor cells and the mechanism of drug-resistant mediated by transcription factors GATA4 and ETS1 should be further identified." (PMID 26625313, 2016). "These discoveries inspired us to design an artificial hTERT promoter as a tumor-specific element regulated by ETS-1." (PMID 26743236, 2016). "The dual luciferase assay system was used to verify the driven efficiency and tumor-specificity of the artificial hTERT promoter and to confirm the relationship between ETS-1 and the driven efficiency of the artificial hTERT promoter." (PMID 26743236, 2016). "Subsequent analysis of eight fresh frozen tissues from LSCC patients undergoing resection revealed that ETS-1 mRNA and protein expression were significantly higher in the tumor tissues as compared to the adjacent normal counterparts (all p ≤ 0.004)." (PMID 26826553, 2016). "Upon binding, various kinases, including PI3K, and MAP3K14, and several transcription factors such as nuclear factor-kappa B (NF-kB), AP-1 and Ets-1 are activated leading to OPN-induced tumor growth, angiogenesis, tumor metastasis and inhibition of apoptosis." (PMID 25749383, 2015). "As a crucial transcription factor, ETS-1 widely expressed in lymphocytes, vascular endothelial and various invasion tumor cells." (PMID 26241881, 2015). "Aberrant expression of ETS-1 was found to be correlated with malignant cancer behaviors such as tumor proliferation, invasion, migration and angiogenesis." (PMID 25421630, 2015). "Taken together, our results provide evidence of an Rb1-dependent Ets1-Zeb1 amplification loop in thymocyte differentiation and tumor invasion." (PMID 25880398, 2015).
tumor (continued). "TIP30 is able to interact with Ets-1 and inhibit Ets-1-mediated transactivation of osteopontin, an important molecule for tumor metastasis in HCC." (PMID 25544767, 2015). "Hashiya confirmed that Ets-1 played an important role in promoting the tumor angiogenesis through regulating angiogenesis factor, such as VEGF, Ang2, and so on." (PMID 25264483, 2014). "Taken together, this evidence indicates that the proto-oncoprotein ETS1 plays an important role in tumor chemoresistance via a number of different mechanisms." (PMID 24602286, 2014). "Since many papers have shown that both integrin αvβ6 and transcription factor Ets-1 participate in the regulation of malignant tumor biological behavior, therefore we performed the immunohistochemical assessment of integrin αvβ6 and transcription factor Ets-1." (PMID 25264483, 2014). "As a crucial transcription factor widely expressed in lymphocytes and vascular endothelial, lacteal glandular epithelium and various invasion tumor cells, ETS1 regulates the development, senescence and death of many immune cells." (PMID 24708692, 2014). "Our results suggest that transcription factors E2F4, AR and ETS1 are potential key regulators in tumour progression." (PMID 24523864, 2014). "Park showed that the expression of Ets-1 has intimate correlation with tumor cell invasion and metastasis." (PMID 25264483, 2014). "In some tumor types, expression of ETS1 is either upregulated or observed exclusively in invasive, higher grade tumors." (PMID 24602286, 2014). "To date, an increasing number of clinical studies have shown the important roles of Ets1 in tumor development and progression of various solid tumors." (PMID 23383271, 2013). "Ets1 transcriptionally promotes proteases involved in extracellular matrix degradation, a key component of tumor invasion." (PMID 23874775, 2013). "As anticipated, due to the established estrogen-dependence of MCF7 cells, mice implanted with estradiol-releasing pellets exhibited increased tumor growth for both control and Ets1-expressing MCF7 cells." (PMID 23874775, 2013). "In Dittmer study reported that over-expression of ETS1 would promote tumor invasion due to its ability to activate the MMP1, MMP3, MMP9 and uPA as well as of VEGF in tumorigenesis." (PMID 23405089, 2013). "Ets-1 is a transcription factor that regulates many genes involved in cancer progression and in tumour invasion." (PMID 23405229, 2013). "Ets1 acts as a cSCC tumor promoting gene by inducing cSCC cell proliferation in transgenic mice over-expressing Ets1." (PMID 23646287, 2013). "Ets1-expressing MCF7 tumors grown in the mammary fat pads of nude mice exhibited increased rates of tumor growth (7.36±2.47 mm3/day) compared to control MCF7 tumors (2.52±1.70 mm3/day), but maintained their dependence on estradiol for tumor growth." (PMID 23874775, 2013). "Ets1-expressing/estradiol treated tumors showed significantly increased tumor volumes compared to control/cellulose tumors beginning 32 days post tumor implantation and were significantly different from control/estradiol tumors from 34 days post implantation." (PMID 23874775, 2013). "When the study was terminated at eight weeks, mean tumor volume of Ets1/estradiol tumors was more than twice that of control/estradiol tumors." (PMID 23874775, 2013). "The pathological expression of Ets-1 is partly responsible for the proliferation and invasion abilities of tumour cells." (PMID 23405229, 2013). "Together, these data further strengthen the proposed linkage between NO and Ets-1 signaling and suggest that their interaction is a major promoter of tumor metastasis and requires further investigation." (PMID 22971289, 2012). "A similar regulation has been shown in Ki-RAS-transformed prostate cells where the activation of the RAF/MEK/ERK signaling pathway induces ETS-1 phosphorylation at T38, nuclear translocation and tumor progression." (PMID 21711453, 2011).